CD4 (CD4 molecule)
Diseases named in the same sentence as CD4 in open-access papers (continued):
Sharing a sentence is not in itself a finding about the gene and the disease.
aseptic meningitis (2 papers, 2010 to 2018). Inflammation of the membranes surrounding the brain and spinal cord without a bacterial pathogen. "The ratio of CD4+/CD8+ T cells in aseptic meningitis is typically approximately 3:1; however, it was unusually low in our case (approximately 1:1)." (PMID 30217214, 2018). "The ratio of CD4+/CD8+, which is typically 3:1 in aseptic meningitis, was unusually low (approximately 1:1) in both sections." (PMID 30217214, 2018).
asplenia (2 papers, 2021 to 2025). "It took the form of an aberrant lymphocyte population: a reduction in T CD4/CD8 lymphocyte count (Case 1), a reduction in the number of T CD4/CD8 lymphocytes and deficiency of IgG1 (Case 2) or anatomic asplenia (Case 9)." (PMID 35011785, 2021). "However, his immune function might be overestimated by CD4 lymphocytes due to asplenia." (PMID 40337277, 2025).
autoimmune glomerulonephritis (2 papers, 2018 to 2024). An autoimmune form of glomerulonephritis (disease). "Similarly, MHC-II+ monocytes interact with effector CD4+ T cells via antigen presentation in an intravascular niche, leading to autoimmune glomerulonephritis in a mouse model." (PMID 38641668, 2024). "However in established autoimmune glomerulonephritis, further mechanisms of antigen recognition, including antigen presentation by glomerular endothelial cells with upregulated MHCII expression could contribute to activation of CD4+ T cells." (PMID 29467472, 2018).
autoimmune neurological diseases (2 papers, 2025). "In particular, CD4+ EOMEShi is a compelling NINT culprit as CD4+ cytotoxic T cells have been reported in association with autoimmune neurological diseases." (PMID 41282927, 2025). "This article primarily delves into the development and function of CD4+CD25+ Tregs, the role of Tregs in neurological autoimmune disease pathology, basic methods for enhancing therapies, and recent advancements and challenges in cellular therapy for neurological autoimmune diseases." (PMID 40525111, 2025).
autoimmune oophoritis (2 papers, 2015 to 2020). Autoimmune oophoritis is a rare cause of primary ovarian insufficiency (POI). "We found that AMHR2-CD immunization of C57BL/6 females induced a prominent antigen-specific proinflammatory CD4+ T cell response that resulted in a mild transient autoimmune oophoritis that resolved rapidly with no detectable lingering adverse effects on ovarian function." (PMID 26618181, 2015).
brain glioma (2 papers, 2021). A malignant glioma that involves the brain. "B7-H5 knockout mice were highly resistant to tumor induction in a murine brain glioma model through activating CD4+ T-cell-mediated immunity." (PMID 34537815, 2021). "A study in brain glioma patients indicated that CTLA-4 is highly expressed on T cells, specifically the effector CD4 + T cells." (PMID 34006227, 2021).
Burkholderia Infections (2 papers, 2020 to 2021). Infections with bacteria of the genus BURKHOLDERIA. "Although CD4+ responses appear to be important for clearing Burkholderia infections, studies at the cellular level show that antibodies alone are not sufficient to clear infection from macrophages, while IFN-γ helps to eliminate the intracellular infection." (PMID 33322641, 2020).
C. m (2 papers, 2015 to 2024). "Our previous data show that iNKT cells promote NK cells and CD4/CD8 T cells to produce IFN-γ in the C. m. lung infection model." (PMID 38247825, 2024). "We found lung Cm infection did induced IL-9 production by CD45+ and more specifically CD4+ T cells (CD4+CD3ε+)." (PMID 25646821, 2015).
CAEBV infection (2 papers, 2011 to 2018). "The infiltrating cells show usually a CD8+, CD3+, CD2+, CD56− phenotype with expression of cytotoxic granules TIA1 and granzyme B. Rare cases of CD4+ or mixed CD4+ and CD8+ phenotype have been described usually occurring in the setting of CAEBV infection." (PMID 29518976, 2018). "In contrast, among patients with T cell LPD after CAEBV infection two were CD4+, one was CD45RO+ and one presented with an admixture of CD8+ and CD4+ lymphocytes; three cases presented with monoclonal patterns with regard to rearrangement of both TCRα genes and EBV genome." (PMID 21649898, 2011).
Castleman disease (2 papers, 2012 to 2015). Castleman disease (CD) is a benign lymphoproliferative disorder that may present as a localized or multicentric form. "Interestingly, two patients in our study with coexisting KS and Castleman disease had CD4 counts above 350 cells/ul." (PMID 26091519, 2015).
cholestatic jaundice (2 papers, 2009 to 2017). "According to animal studies, obstructive jaundice downregulates the numbers of CD4+ and CD8+ T-lymphocytes and MAdCAM-1 expression in the lamina propria." (PMID 29209365, 2017).
Chronic constipation (2 papers, 2021 to 2024). Constipation for longer than three months with fewer than 3 bowel movements per week, straining, lumpy or hard stools, and a sensation of anorectal obstruction or incomplete defecation. "CD patients with visceral obesity has higher incidence of chronic constipation (81% vs. 57%, P = 0.028), higher IL-6 levels (15.28 pg/ml vs. 9.429 pg/ml, P = 0.007) and lower CD4+ T cells (32.7% vs. 44.0%, P < 0.001)." (PMID 33675295, 2021). "A study revealed elevated counts of CD3+, CD4+, CD8+, and CD25+ T cells, along with increased intestinal permeability, in patients with functional constipation, implying that the intestinal immune system is abnormal in patients with chronic constipation." (PMID 38289380, 2024).
chronic lung allograft dysfunction (2 papers, 2019 to 2024). Chronic lung allograft dysfunction encompasses a range of pathologies that cause a transplanted lung to not achieve or maintain normal function. "Flow cytometry analysis of paired PBMC and BAL samples from a lung transplant recipient with chronic lung allograft dysfunction (CLAD) demonstrated the panel’s capability to identify CD4 and CD8 T cells in both PBMC and BAL." (PMID 38473722, 2024).
chronic mucocutaneous candidiasis (2 papers, 2014 to 2016). "Chronic mucocutaneous candidiasis (CMC) patients with a dominant-negative STAT3 mutation present with a decreased number of central memory CD4+ and CD8+ lymphocytes and an increased number of naive T cells." (PMID 27703456, 2016).
chronic spontaneous urticaria (2 papers, 2024 to 2025). "In a study of patients with chronic spontaneous urticaria on OMA, a reduction in the number of both naïve CD4+ and CD8+ T cells was found in favor of an increase in memory CD4+ T cells and effector CD8+ T cell populations." (PMID 41488545, 2025).
chronic thromboembolic pulmonary hypertension (2 papers, 2022 to 2023). Chronic thromboembolic pulmonary hypertension (CTEPH) is characterized by the persistence of thromboemboli in the form of organized tissue obstructing the pulmonary arteries. "The decreased CD3 and CD8 levels and the increased CD4/CD8 ratio were discovered in the s acute pulmonary embolism and chronic thromboembolic pulmonary hypertension (CTEPH) patients, meaning the dysfunction of CD3+ CD8+ T Cell immunity." (PMID 37465678, 2023).
clear cell ovarian cancer (2 papers, 2022 to 2023). "In advanced clear cell ovarian cancer, an increased infiltration of CD4+ T cells at the leading edge and stroma was significantly associated with poorer OS." (PMID 37761986, 2023). "In ovarian clear cell carcinoma, ACY-1215 was found to activate CD4 and CD8 T cells and increase IFNγ+ CD4 and CD8 T cells, as a result enhancing the immune killing effect." (PMID 35652048, 2022).
CNS demyelinating diseases (2 papers, 2024 to 2025). "Alternatively, the polysaccharide A of Bacteroides fragilis can directly induce differentiation of naïve CD4+ T cells to IL-10 producing FoxP3 + Treg cells, thereby conferring protection against CNS demyelinating diseases." (PMID 38352704, 2024).
colorectal polyps (2 papers, 2014 to 2022). "Our data also show a good correlation between the presence of CD4+ cells in colorectal polyps and regressing polyps." (PMID 24867408, 2014). "In addition, ingestion of bLF resulted in an increase in the number of CD4+ and NK cells in colorectal polyps." (PMID 24867408, 2014). "To date, this is the first study describing the CD4 T cell response towards PASD1 peptides in CRC and colorectal polyps patients." (PMID 37529004, 2022).
congenital hypothyroidism (2 papers, 2017 to 2022). A thyroid hormone deficiency present from birth. "In congenital hypothyroidism mouse model with high level of TSH, one study demonstrated the lower CD8+ percentage and higher CD4+ percentage in thymocytes compared with euthyroid mice." (PMID 35804367, 2022).
congenital toxoplasmosis (2 papers, 2020 to 2025). Toxoplasma infection that is present from birth. "In this context, our results have shown that the production of IFN-γ by CD4+ T-cells after short-term stimulation with T. gondii antigen has high accuracy for the early diagnosis of congenital toxoplasmosis." (PMID 33028847, 2020). "In addition, high global accuracy (AUC = 0.9) with elevated sensitivity (Se = 98%) was also reached by using the total frequency of in vitro IFN-γ-producing T. gondii-specific T-cells (∑ IFN-γ+ CD4+ & CD8+) as a biomarker of congenital toxoplasmosis." (PMID 33028847, 2020). "Thus, while the assessment of IFN-γ producing NK cells provide a putative biomarker for early prognosis of congenital toxoplasmosis, the analysis of IL-5+CD4+ T-cells upon T. gondii antigens stimulation is a potential prognostic marker of ocular involvement in infant with congenital toxoplasmosis." (PMID 33028847, 2020). "Combined analyses of CD4+CD25+ T-cells and CXCL9, and IFN-γ production by CD4+ and CD8+ T-cells have even higher accuracy as biomarkers of congenital toxoplasmosis." (PMID 33028847, 2020). "Furthermore, the analysis of in vitro T. gondii-specific IL5+CD4+ T-cells and IFN-γ+NK-cells displayed a high accuracy for early prognosis of ocular lesion in infant with congenital toxoplasmosis (Global Accuracy/AUC = 0.8 and 0.9, respectively)." (PMID 33028847, 2020). "Finally, the contemporaneous analysis of T. gondii-specific IL-5+CD4+ T-cells and IFN-γ+NK-cells serve as an early prognosis tool of ocular involvement in infant with congenital toxoplasmosis." (PMID 33028847, 2020). "We propose the levels of CXCL9 and CXCL10, the frequencies of CD4+CD25+ T-cells and the frequency of T. gondii-specific IFN-γ producing CD4+ T-cells presented as biomarkers able to distinguish with high accuracy infants with congenital toxoplasmosis from uninfected healthy controls." (PMID 33028847, 2020). "Moreover, the combined stepwise analyses of CD4+CD25+ T-cells and CXCL9 or the total frequency of in vitro IFN-γ-producing T. gondii-specific T-cells further improve the accuracy of the diagnosis of congenital toxoplasmosis." (PMID 33028847, 2020). "A prominent pro-inflammatory response of CD4+ and CD8+ T-cells, characterized by high levels of IFN-γ has been reported during congenital toxoplasmosis; in cases without ocular involvement as well as in those with active or cicatricial retinochoroidal lesion." (PMID 33028847, 2020).
Constipation (2 papers, 2024 to 2025). Infrequent or difficult evacuation of feces. "Abnormal proliferation of IL-17A+ CD4+ T (Th17) cells is a core feature of constipation-related inflammation." (PMID 41050658, 2025). "In contrast, patients reporting mild to moderate dyschezia exhibited higher total T cell (p = 0.016) and CD4 T cell counts (p = 0.043), along with lower NK cell percentages (p = 0.026)." (PMID 39337624, 2024). "EM patients without dyschezia exhibited increased CD4, CD8, and total T cell counts (p = 0.048; p = 0.019; and p = 0.016, respectively) in PB." (PMID 39337624, 2024). "Locally, PF analysis demonstrated lower CD56+ CD4 T cells in patients without dyschezia compared to both controls and EM patients with dyschezia (p = 0.005)." (PMID 39337624, 2024).
cryptogenic organizing pneumonia (2 papers, 2021 to 2025). Cryptogenic organizing pneumonia (COP) is a form of idiopathic interstitial pneumonia characterized pathologically by organizing pneumonia (OP) that presents with non-specific flu-like symptoms, as well as cough and dyspnea and where no etiological agent is found. "Due to of the low CD4+ T-cell count and the atypical disease course with constant migration of the lung lesions, pneumocystis jirovecii pneumonia (PJP) and cryptogenic organizing pneumonia (COP) were suspected." (PMID 40018346, 2025).
cutaneous vasculitis (2 papers, 2021 to 2022). Inflammation of the blood vessel wall characterized by palpable purpura. "We observed that the mean fluorescence intensity (MFI) of PD-1 and CTLA-4 in the CD4+ T-cell population was notably increased in patients with cutaneous vasculitis compared to the HD." (PMID 34625602, 2021). "Histologically, PD-L1 was also highly expressed in the vessels of the dermis in patients with cutaneous vasculitis, and CD4+ and CD8+ T-cells were located adjacent to the PD-L1-expressing vessels." (PMID 34625602, 2021). "Histologically, PD-L1 was highly expressed in the vessels in the skin along with CD4+ and CD8+ T-cell infiltration in patients with cutaneous vasculitis." (PMID 34625602, 2021). "We observed that the percentage of Ki67+cells within the CD8+ cell population in patients with cutaneous vasculitis was higher than in HDs, while the percentage in the CD4+ cell population was not significantly different." (PMID 34625602, 2021).
deficiencies (2 papers, 2023 to 2025). "This may be because a reduction in CD4 cell counts leads to cellular and, consequently, humeral deficiencies." (PMID 38087261, 2023).
dysferlinopathy (2 papers, 2022). "Compared to normal controls, dysferlinopathy muscles had significantly more T cells (including CD4 T cell, CD8 T cell, natural killer T cell, regulatory T cell, type I T helper cell), macrophages, and dendritic cells." (PMID 36203997, 2022). "In agreement with our results, previous studies have shown that CD4 cells, macrophages, MHC-I and C5b-9 are positive in immunohistochemically stained dysferlinopathy muscles." (PMID 36203997, 2022).
eating disorder (2 papers, 2021 to 2022). A broad group of psychological disorders with abnormal eating behaviors leading to physiological effects from overeating or insufficient food intake. "After refeeding during 6 weeks of multimodal therapy, CXCR3 levels normalized on CD4+ T cells in AN suggesting that this immune alteration is linked to the pathophysiology of this eating disorder." (PMID 36226111, 2022). "In one study involving patients with AN, BN, and healthy controls, the CD4/CD8 T-cell ratio was found to be significantly lower in the BN group, relative to the AN group, with both eating disorder groups having lower CD4/CD8 ratios than healthy controls." (PMID 33546416, 2021).
endocervical carcinoma (2 papers, 2020 to 2022). A carcinoma that arises from epithelial cells of the endocervix. "However, CTHRC1 was not correlated with B cells (r=−0.053, p=3.80e-01), CD4+ T cells (r=0.021, p=7.27e-01), CD8+ T cells (r=−0.063, p=2.98e-01), dendritic cells (r=0.041, p=4.98e-01), and neutrophils (r=−0.037, p=5.42e-01) in cervical and endocervical cancers." (PMID 33628726, 2020).
eosinophilic pneumonia (2 papers, 2017 to 2020). An inflammatory lung disorder characterized by an increased number of eosinophils in the lungs. "Thus, memory-type ST2+CD4+ T cells are steroid-resistant and appear to play a critical role in steroid-resistant types of eosinophilic lung inflammation, such as chronic-type eosinophilic pneumonia." (PMID 28754914, 2017). "Therefore, we wanted to evaluate the effect of steroid on the lung tissue-localized memory-type ST2+CD4+ T cells using our eosinophilic pneumonia model induced by intratracheal administration of IL-33." (PMID 28754914, 2017). "Thus, our results highlighted the fact that memory-type ST2+CD4+ T cells are involved in the pathogenesis of steroid-resistant eosinophilic pneumonia induced by IL-33." (PMID 28754914, 2017). "Thus, lung-resident memory-type ST2+CD4+ T cells could be a potential therapeutic target for the patients with steroid-resistant allergic inflammation such as eosinophilic pneumonia." (PMID 28754914, 2017). "Thus, the process of IL-33-induced activation of memory-type ST2+CD4+ T cells may be a potential therapeutic target for steroid-resistant recurrent eosinophilic lung inflammation, including eosinophilic pneumonia." (PMID 28754914, 2017). "The increase in G-CSF and eotaxin along with the increase in CD4 cells in BALF suggest that acute exposure may be leaning toward the Th2 pathway, implicating potential eosinophilic pneumonia with prolonged exposure." (PMID 32605182, 2020).
epithelioid mesothelioma (2 papers, 2017 to 2024). "Recent studies have shown that a high proportion of CD4+ T cells in epithelioid mesotheliomas is associated with a better prognosis." (PMID 39410037, 2024). "In summary, our data demonstrate for the first time an association of survival with high CD4+, low FOXP3+, high CD20+, low NP57+ and low CD68+ counts in epithelioid mesothelioma, treated with palliative intent." (PMID 28817839, 2017). "More recently, a larger series demonstrated tumour CD4+ T-cell infiltration confers a survival advantage in epithelioid mesothelioma." (PMID 28817839, 2017).
exanthem subitum (2 papers, 2020 to 2022). "In addition, HHV-6 and -7, which are causative viruses of exanthem subitum, infect several immunocytes, including monocytes/macrophages and CD4+ T cells, the latter of which have been identified as a candidate secreting TIMP-1 in vitro." (PMID 36670630, 2022).
factor IX deficiency (2 papers, 2020 to 2022). "Further analyses of Treg CD4+ lymphocyte sub-populations in hemophilia B mice reveal a marked increase in the frequency of CD4+CD25−FoxP3−LAP+ T cells (but not of CD4+CD25+FoxP3+ T cells) in the lamina propria of the small but not large intestine." (PMID 32508814, 2020).
Fanconi anemia (2 papers, 2021 to 2022). Fanconi anemia (FA) is a hereditary DNA repair disorder characterized by progressive pancytopenia with bone marrow failure, variable congenital malformations and predisposition to develop hematological or solid tumors. "Notably, mutations in the Fanconi Anemia pathway were associated with an increased co-localization between tumor cells and CD4 cells." (PMID 33791196, 2021).
Fibroadenoma (2 papers, 2016 to 2022). A benign tumor of the breast characterized by the presence of stromal and epithelial elements. "The percentages of CD4+ T cells in PBMCs of health individuals (19.90 ± 9.02%), fibroadenoma (FIBma) (22.98 ± 7.51%) and IBCa patients (20.74 ± 8.84%) were comparable (P > 0.05)." (PMID 27762298, 2016).
fibrous tumors (2 papers, 2020 to 2022). "However, this hypothesis can be rejected because CD4+ cells were not inhibited in infiltration into fibrous tumors." (PMID 34997450, 2022).
focal segmental glomerulosclerosis (2 papers, 2010 to 2021). A renal disorder characterized by sclerotic lesions in the glomeruli. "Where ICAM-1 and P-selectin were present, primarily CD4+ T cells were also detected, except in two cases of focal segmental glomerulosclerosis and in one case of membranoproliferative glomerulonephritis." (PMID 20459816, 2010).
Follicular Cyst (2 papers, 2014 to 2020). Cyst due to the occlusion of the duct of a follicle or small gland. "Post-administration of KOK further decreased the increasing of body weight by DHEA, more conclusively reduced the number of follicular cyst in the ovaries, and inhibited the activation of CD4 (+) T lymphocytes in lymph nodes than that of pre-administration of KOK." (PMID 24520334, 2014).